TNF (tumor necrosis factor)
Diseases named in the same sentence as TNF in open-access papers (continued):
Sharing a sentence is not in itself a finding about the gene and the disease.
liver disease (continued). "In this study, we showed an NF-κB-independent role of Bcl-3 in the liver, and our work suggests deletion of Bcl-3 greatly ameliorates TNF-induced liver injury, which provides a potential therapeutic target for various liver diseases." (PMID 34853447, 2022). "TNF-α and IL-6 are inflammatory mediators that contribute to the pathological complications observed in several hepatic diseases." (PMID 35877426, 2022). "These properties of TNF make it necessary to study the exact molecular function of TNF and its receptors in a specific hepatic disease to identify the most relevant target for therapeutic intervention." (PMID 35122118, 2022). "Increased levels of TNF-α are observed in the plasma of CHB patients and have been associated with CHB-related liver disease progression." (PMID 36052277, 2022). "Alcohol can induce the increase of endotoxin level, activate Kupffer cells, and trigger the excessive production of TNF-α, IL-1β, and IL-6, which participate in the pathogenesis of liver diseases." (PMID 35409071, 2022). "The inflammation observed in liver diseases including alcoholic hepatitis and acetaminophen overdose includes the activation of acute responses with IL-1 beta, IL-6, and TNF alpha." (PMID 35805080, 2022). "TNF-α and NO have a vital function in inducing inflammation in oxidative stress-related hepatic diseases, promoting programmed cell death and fibrosis." (PMID 34347571, 2021). "In anti-CD40 mAb-induced necro-inflammatory liver disease, the importance of TNF-α has been emphasized." (PMID 34440067, 2021). "Considerable evidence supports that TNF-α and IL-1β are related to liver diseases’ pathogenesis by activating the NF-κB signaling pathway." (PMID 33671028, 2021). "Proinflammatory cytokines, particularly IL1 and TNF.α, play important roles in several stages of liver disease to reduce disease severity." (PMID 34237551, 2021). "Variceal enlargement of superficial abdominal vessels secondary to portal hypertension was observed in one patient (Patient 32), with noticeable improvement with anti-TNF treatment." (PMID 35095905, 2021). "Liver disease progression is related to systemic inflammation, leading to impaired dendritic cell activity, increased tumor necrosis factor (TNF)- and interferon (IFN)-γ-expressing lymphocytes, and depletion of interleukin (IL)-17-producing T helper cells." (PMID 34769109, 2021). "Various types of proinflammatory markers like TNF-alpha and IL-6 have been found to contribute to the pathogenesis of liver diseases." (PMID 33531877, 2021). "Tumor Necrosis Factor-α (TNF-α) is an important inflammatory cytokine in the development of liver disease." (PMID 33228594, 2020). "It has been shown that the cytokine TNF-α facilitates hepatocyte proliferation and is involved in progress of advanced stages of liver disease." (PMID 33262767, 2020). "Elevated levels of TNF-α play several crucial roles in the development of liver diseases through the upregulation of proinflammatory cytokines and the expression of lipid metabolic and fibrogenesis markers in the livers of mice." (PMID 31001563, 2019). "Accumulating studies suggest that portal hypertension, prostaglandins (PGs), tumor necrosis factor-α (TNF-α) and excessive nitric oxide (NO), oxygen free radicals and lipid peroxidation are implicated in the pathogenesis of PHG2,5,6." (PMID 31582729, 2019). "In detail, the ECCO guidelines and the American Association for the Study of Liver Disease (AASLD) recommendations advise HBsAg, anti-HBsAg and anti-HBc testing for all patients before starting anti-TNF-α therapy." (PMID 30060508, 2018).
liver disease (continued). "Considerable evidence has accumulated to suggest that the NF-κB signaling pathway contributes to the pathogenesis of liver inflammatory diseases through the activation of TNF-α, IL-6, and IL-1β." (PMID 29849889, 2018). "On the other hand, anti-TNF-α agents have also been used for treating the severe stages of hepatic diseases such as alcoholic hepatitis (AH) and non-alcoholic fatty liver disease (NAFLD)." (PMID 30060508, 2018). "TNFα and IFNγ are known to be significantly up‐regulated in inflammatory liver disease and important activators of endothelium during cellular injury." (PMID 27770554, 2017). "The overexpression of TNF-α and IL-1β was found to be enhanced in both animal models and patients with liver disease." (PMID 28387740, 2017). "After hepatorenal syndrome, plasma concentrations of tumor necrosis factor-α increased by two-fold, and α1-AR was significantly activated in the renal artery." (PMID 29312606, 2017). "Although a heap of data was published on the role of TNF-α in liver disease, when and how this mediator induces intracellular apoptotic or antiapoptotic pathways are still nonanswered questions." (PMID 27293514, 2016). "This link will have relevance to multiple diseases, since inflammatory stimuli such as TNF-α and LPS have been shown to play roles in many liver diseases, including viral hepatitis (19, –, 21)." (PMID 27009955, 2016). "Liver disease is also characterized by increased production of inflammatory cytokines, including TNF-α and IL-629." (PMID 27456065, 2016). "By blocking TNFα-related effects, thalidomide not only inhibits hepatic fibrogenesis but improves peripheral vasodilatation and portal hypertension in cirrhotic rats." (PMID 26820153, 2016). "Whereas various pro-inflammatory cytokines are increased during liver injury, TNF-α has particularly been shown to be involved in these liver diseases." (PMID 27598994, 2016). "There is evidence supporting an important role of cytokines, including interleukin- (IL-) 1α, IL-6, and tumor necrosis factor (TNF) in various aspects of inflammatory liver diseases." (PMID 26448742, 2015). "For example, the induction of TNF-α causes phosphorylation of IRS-1 at Ser312 and impedes insulin signaling, especially in HCV patients with more severe liver disorders." (PMID 25645159, 2015). "HCV patients have an elevated serum level of TNF-α, and this level is positively correlated with the severity of liver diseases." (PMID 26023919, 2015). "It was reported that the proinflammatory cytokines like TNF-α play an important role in the pathogenesis of a large number of liver diseases." (PMID 25088145, 2014). "TNF-α levels were shown to be higher in obese and diabetic individuals and to correlate with insulin resistance and liver disease." (PMID 24918094, 2014). "Cytokines such as IL-1β, TNF-α, IL-8 and IL-6 have been involved in chronic liver inflammation and pathogenesis of various liver diseases; among which IL-6 and TNF-α, are thought to be most important." (PMID 24918094, 2014). "Increased circulating levels of IL-6 and TNF-α have been found in animal models and patients with liver disease including HCC." (PMID 24918094, 2014). "While similar to previous study, pretreatment with Bifendate (150 mg/kg), an agent being applied clinically to treat liver disease, abolishes the positive signals of TNF-α." (PMID 24090365, 2013). "Increasing evidence suggests that TNFα is involved in the pathogenesis and progression of liver disease of different aetiology." (PMID 23394097, 2013). "Since inhibition of NF-κB sensitizes hepatocytes to TNFα-induced cell death, it is important to determine the effect of metformin on NF-κB activation, prior to its use in inflammatory (TNFα-mediated) liver diseases." (PMID 23951244, 2013). "The efficacy of the inhibition of APE1 redox activity in blocking TNF-α and FAs induced inflammatory response opens new perspectives for treatment of inflammatory-based liver diseases." (PMID 23967134, 2013).
liver disease (continued). "MMP-9, a consequent molecules in TNF-α signaling, is known as an indicator playing important roles in hepatic disorders." (PMID 23555760, 2013). "Although TNFα can kill hepatocytes during such liver diseases, the healthy liver usually has defense systems against TNFα-induced cell death." (PMID 22666632, 2012). "Considerable evidence suggested that TNF-α and IL-6 contribute to the pathogenesis of liver inflammatory diseases by activating the NF-κB signaling pathway." (PMID 23243434, 2012). "Type 1 diabetic patients with the liver disease often have systemic increases of inflammatory cytokines such as TNF-α." (PMID 23251339, 2012). "Increased activation of the inflammatory cascade was found in chronic alcoholics with liver disease where blood monocytes produced increased levels of the pro-inflammatory cytokine TNF alpha." (PMID 21962237, 2011). "We previously showed that a key mediator of NPC liver disease is tumor necrosis factor (TNF) α, which is involved in both proinflammatory and apoptotic signaling cascades." (PMID 20886067, 2010). "The direct correlation between TNF-α concentrations and the rate of apoptosis has been described in several types of liver diseases characterized by cell necrosis and death." (PMID 15826301, 2005). "Notably, TNF-α is regarded as playing a key pro-inflammatory role in the pathophysiology of liver disease." (PMID 41282626, 2025). "In liver disease, innate immune cells respond to hepatic insults by activating cell-intrinsic inflammasomes via toll-like receptors and NF-κB, and by releasing pro-inflammatory cytokines (such as IL-1β, IL-18, TNF-α and IL-6)." (PMID 38908436, 2024). "The negative correlation with key inflammatory cytokines, notably those involved in acute and chronic inflammatory responses and liver diseases, like IL-1β, IL-18, and TNF-α, reinforces the hypothesis that CR1L might have a protective role in AH." (PMID 38573776, 2024). "First, its retrospective design might have introduced biases due to unmeasured confounding factors, such as liver disease, post-transplant status, solid and/or hematological malignances, and several biomarkers including IL-6 and tumor necrosis factor α." (PMID 39695439, 2024). "A few patients with refractory disease (including severe liver diseases) responded to TNF-blockade." (PMID 37669122, 2024). "Tumor necrosis factor (TNF) is a major pro‐inflammatory cytokine that not only promotes immune‐mediated virological control but also causes hepatocellular injury, cirrhosis, and ultimately HCC during the development of liver disease." (PMID 39315805, 2024). "TNF-α is a crucial inflammatory cytokine in the development of liver disease." (PMID 37759583, 2023). "The increase in TNF-RII concentration in our patients may reveal that HCV-related liver disease involves immunological mechanisms, which including TNF system activation, and may reflect the degree of inflammation and progression of HCC." (PMID 37798688, 2023). "Collectively, we establish that Kindlin-2 acts as a novel intrinsic inhibitor of the TNF pathway to maintain liver homeostasis and may define a useful therapeutic target for liver diseases." (PMID 36622102, 2023). "TNF, a pro-inflammatory cytokine, is involved in the pathophysiology of liver disease." (PMID 37798688, 2023). "Elevated tumor necrosis factor alpha is not only an important cytokine in the pathogenesis of IBD but also one of the main proinflammatory factors involved in the earliest phases of a variety of liver diseases." (PMID 35566749, 2022). "Due to expanded and inflamed abnormal adipocytes, increased adipocytokines such as TNF-α and leptin and decreased adiponectin secretion could contribute to apoptosis and necrosis in hepatocytes, progressing to liver disease." (PMID 35251036, 2022).
liver disease (continued). "Thus, therapeutic strategies that interfere with inflammatory markers, such as anti-tumor necrosis factor (TNF)-α treatment (e.g., infliximab and etanercept) and interleukin-24 therapy, are being investigated for the treatment of liver diseases." (PMID 35892639, 2022). "Therapies that reduce pro-inflammatory responses, namely TNFα, could have important clinical implications to reduce hepatosteatosis and progression of severe liver disease." (PMID 36865784, 2022). "When mast cells are activated, they degranulate and release many mediators, such as histamine, tryptase, chymase, transforming growth factor-β1 (TGF-β1), tumor necrosis factor–α(TNF-α), interleukins cytokines, and other substances that mediate the progression of liver disease." (PMID 36176778, 2022). "Some studies showed that the liver disease of a patient was likely triggered by a host of proinflammatory cytokines, such as interleukin-1β (IL-1β), interleukin-6 (IL-6), and tumor necrosis factor (TNF-α), that contribute to hepatocellular damage." (PMID 35897657, 2022). "In the context of liver diseases, cytokines have been assigned fundamental properties reflecting common function, including proinflammatory cytokines (e.g. IL‐1α, IL‐1β, TNF‐α, and IL‐2), immunoregulatory cytokines (e.g. IFN-γ), and anti-inflammatory cytokines (e.g. IL-10 and IL-4)." (PMID 33841403, 2021). "Although not tested in liver disease-associated muscle wasting yet, the strategy that depends on TNFα signal inhibition would have an advantage in liver disease over cancer cachexia." (PMID 33414474, 2021). "Liver disease continued to progress in 1 patient (Patient 37) who had pre-existing portal hypertension and focal regenerative hyperplasia prior to the initiation of a TNF inhibitor." (PMID 35095905, 2021). "The exposure to endotoxins activates macrophages via Toll-like receptor 4 (TLR4), leading to a greater production of proinflammatory cytokines and chemokines including tumor necrosis factor-alpha, interleukin (IL)-6, and IL-8, which play key roles in the progression of liver diseases." (PMID 34203178, 2021). "It is unlikely that anti-TNF therapy contributed to the progression of this patient’s liver disease, since there are reports that anti-TNF therapy has been beneficial in patients with hepatitis B and C-related liver disease and animal models of steatohepatitis." (PMID 35095905, 2021). "The liver disease in this patient initially progressed despite treatment with a TNF inhibitor." (PMID 35095905, 2021). "Inflammatory mediators including TNF-α, IL-1β, and IL-10 may influence the progression of liver disease." (PMID 33117360, 2020). "Gram-negative LPS-producing bacteria, such as Oscillibacter, may activate bacterial translocation, leading to liver disease; LPS could also elevate levels of TNF-α by activating inflammatory signaling pathways, leading to chronic liver disease." (PMID 29867999, 2018). "In the present study, we have shown that high levels of IL-6, IL-10, and TNF-α could be protective against severe S. mansoni hepatic disease." (PMID 29610679, 2018). "Conversely, the investigation on specific host variables that are connected to TNF-α involvement in inflammatory liver diseases could open new therapeutical horizon to the selection of patients who would benefit from anti-TNF-α use." (PMID 30060508, 2018). "A correlation between TNFα and degree of severity of the liver disease were described." (PMID 29179679, 2017). "Continuous availability of high TNF concentrations under pathophysiological conditions may uncouple this fine-tune regulation and therefore participate in the development of liver diseases." (PMID 28878689, 2017). "In addition to production of ROS, KCs are frequently noted as potent producer of tumor necrosis factor-α (TNF-α), despite the fact that in a majority of liver diseases the actual increase in serum TNF-α levels is very limited." (PMID 28670626, 2017).
liver disease (continued). "Considerable evidence suggests that TNF-α and IL-1β contribute to the pathogenesis of liver inflammatory diseases by activating the NF-κB signaling pathway, suggesting that it may be important to monitor proinflammatory cytokines when studying liver injury." (PMID 26798422, 2016). "In this study, we evaluated whether targeting the TNF-α axis may be useful in ameliorating liver injury parameters and the DR in the context of a steatotic and a cholestatic model of liver disease." (PMID 27824131, 2016). "Moreover, TNF-α is a representative proinflammatory cytokine acting as a detrimental factor in various liver disorders and the presence of TNF-α significantly enhanced the toxicity of APAP to hepatocytes." (PMID 25884831, 2015). "Interestingly, in the Kaplan-Meier analysis, patients with higher circulating TNF-a were more likely to display liver disease progression according to both endpoints, i.e. ALT > 200 IU/L (log rank p = 0.04) and Fib-4 > 1.45 (log rank p = 0.0004)." (PMID 24520976, 2014). "The increased plasma levels of TNF-α have also been found by our group in portal hypertensive rats." (PMID 24633079, 2014). "In rats, a new therapy with the blockade of TNF-α has two direct consequences: it blunts the development of the hyperdynamic circulation and reduces portal pressure in a model of portal hypertension, and reduces the frequency of BT episodes in model of cirrhosis." (PMID 23527251, 2013). "However, in rats, TNF-α blockade appears to blunt hemodynamic disturbances in a model of portal hypertension, and reduce episodes of BT in a model of cirrhosis." (PMID 23527251, 2013). "The proinflammatory cytokine TNFα plays a pivotal role in various inflammatory liver diseases." (PMID 22666632, 2012). "The proinflammatory cytokine TNFα fails to provoke cell death in isolated hepatocytes but has been implicated in hepatocyte apoptosis during liver diseases associated with chronic inflammation." (PMID 21533085, 2011). "We previously showed that tumor necrosis factor (TNF) α is a key mediator of NPC liver disease." (PMID 20886067, 2010). "In this study, we have tested the hypothesis that blocking TNF-α action with an anti-TNF-α monoclonal antibody (CNTO5048) will slow the progression of NPC liver disease." (PMID 20886067, 2010). "In this study, we tested the hypothesis that blocking TNF action with an anti-TNF monoclonal antibody (CNTO5048) will slow the progression of NPC liver disease." (PMID 20886067, 2010). "In portal hypertension, this resistance can be induced by both glucocorticoids and TNF-α." (PMID 17999758, 2007). "For example, adequate levels of TNF and IL-6 are critical for liver regeneration; to inhibit all TNF or IL-6 activity in a patient with severe liver disease could potentially inhibit recovery." (PMID 15706742, 1997). "Moreover, inflammatory cytokines like tumor necrosis factor-alpha and adipokines like leptin, which are often elevated in NAFLD, have been implicated in the progression of liver disease and also exert biological effects in other tissues and conditions, including COPD34–36." (PMID 38734742, 2024). "However, using a combination of biomarkers, e.g., TNFα and ST2/IL-33R, may allow risk stratification of patients who present with mild liver disease and who are averse to biopsy." (PMID 36589452, 2022). "To summarize, caution should be used in the administration of TNFα inhibitors in compensated patients, who need to be monitored by ultrasound imaging; but they are not suitable for patients with decompensated liver disease because of their increased risk of potentially serious infections." (PMID 35203438, 2022). "In addition, LPS induces the secretion of a variety of inflammatory factors, such as TNF-α, IL-6, and TGF-β, which are involved in liver disease caused by LPS, especially in the end-stage liver disease, such as hepatitis B or C virus infection induced liver cancer." (PMID 35965618, 2022).